BRAF (B-Raf proto-oncogene, serine/threonine kinase)
Diseases named in the same sentence as BRAF in open-access papers (continued):
Sharing a sentence is not in itself a finding about the gene and the disease.
melanoma (continued). "In recent decades, aside from BRAF inhibitors and mitogen-activated protein kinase (MAPK) inhibitors—which have been shown to extend overall survival—no other effective treatments have emerged, and most clinical trials for advanced melanoma have failed." (PMID 40699636, 2025). "NRAS mutant melanomas are also characterized by the activation of several signaling pathways (PI3K/AKT, RAL-GEF and cell cycle regulators) in addition to the MAPK pathway, in contrast to BRAF mutants." (PMID 40361349, 2025). "BRAF-mutant melanomas tend to be more aggressive, to grow more rapidly and develop metastases more rapidly, especially brain metastases, compared to BRAFWT melanomas." (PMID 41010758, 2025). "This negative correlation of BRAF and STK11 at the protein level was also observed in our validation subset of BRAFV600E‐mutated human melanomas, supporting the notion of a lack of expression or low amounts of LKB1 in at least 50% of BRAFV600E‐mutated samples." (PMID 39115053, 2025). "In this case, different BRAF-mutant melanoma cell lines were again used, as opposed to our NRAS-mutant melanoma-based study." (PMID 39996721, 2025). "However, with the development of targeted therapies (such as BRAF, MEK, CDK4/6, and C-KIT inhibitors) and immunotherapies (including anti-CTLA4 antibodies and anti-PD-1 antibodies), the systemic treatment of melanoma has been dramatically revolutionized." (PMID 40641936, 2025). "Paradoxically, these wild-type BRAF melanoma cells did not display this enhanced effect, indicating, perhaps, heightened CK2 dependency in cells with BRAF mutations." (PMID 40508214, 2025). "Strikingly, the adhesive capacities and interaction with fibronectin remained unchanged in vemurafenib-treated BRAF-negative melanoma cells." (PMID 40636307, 2025). "Moreover, BRAF inhibitors (vemurafenib, dabrafenib, and encorafenib) cannot be used as single drugs to treat mutant NRAS melanoma, because they paradoxically increase the MAPK/ERK signaling and, consequently, tumor proliferation." (PMID 40141318, 2025). "For example, triple wild-type melanomas, which are melanomas lacking mutations in BRAF, NRAS, and NF1, exhibit markedly low TMB compared to NF1-mutant melanomas." (PMID 40004731, 2025). "Overall, inhibitor performance in melanoma is driven by molecular genotype and influenced by subtype, with BRAF/MEK inhibitors offering the strongest benefit in BRAF V600–mutant cutaneous disease and KIT inhibitors providing a limited but targeted option for select non-cutaneous subtypes." (PMID 41302945, 2025). "Importantly, combining a JNK inhibitor with a BRAF inhibitor was able to overcome MAPK inhibitor resistance, as demonstrated by decreased cell migration and increased cell death compared to melanoma cells when treated with a BRAF inhibitor alone." (PMID 39859271, 2025). "Since no effective treatments have yet been developed for BRAF wild-type melanoma resistant to ICIs, this review aims to explore alternative therapeutic options and evaluate potential treatment strategies beyond currently available ICIs." (PMID 40647561, 2025). "Two melanoma cell lines, A375 and A375 MEK/BRAF inhibitor resistant (A375MEKi) were utilised." (PMID 40135438, 2025). "Small-molecule BRAF inhibitors (e.g., vemurafenib and dabrafenib) and MEK (MAPK/ERK) kinases inhibitors (e.g., trametinib) have distinctly improved the survival of patients suffering from BRAF-mutant cancers such as melanomas." (PMID 39935431, 2025). "However, the invention of targeted therapies such as BRAF/MEK inhibitors and especially immunotherapy has significantly improved therapy options and overall survival rates for melanoma patients." (PMID 40562773, 2025). "Although the combination of vorinostat with the BRAF inhibitor PLX4720 activated caspase-dependent apoptosis in BRAFV600E melanoma, caspase inhibition did not prevent necrotic cell death." (PMID 39935431, 2025).
melanoma (continued). "In a phase 1 study, the feasibility and efficacy of combining BRAF and MEK inhibitors (dabrafenib and trametinib) with the anti–PD-1 antibody pembrolizumab were evaluated in 15 patients with advanced BRAFV600-mutant melanoma who received the triple combination therapy." (PMID 41333480, 2025). "The safety and effectiveness of encorafenib plus binimetinib in Japanese patients with BRAF-mutant malignant melanoma were similar to data reported in COLUMBUS; no new safety concerns were identified." (PMID 39918770, 2025). "One study investigated the relationship between pre-treatment and the early on-treatment detection of BRAF, NRAS and KIT alterations in ctDNA using ddPCR and treatment outcome in 76 melanoma patients treated with nivolumab alone or in combination with ipilimumab." (PMID 39859576, 2025). "Similarly, in melanoma, HDAC10 inhibitors were shown to enhance tumor sensitivity to BRAF inhibitors by upregulating SPARC expression, a key factor in modulating the tumor microenvironment." (PMID 40657362, 2025). "We also tested the modulators of the EMT pathway (spectralflow cytometry of vimentin and MCAM and CD44 expression) to figureout differences between BRAF and non-BRAF positive melanoma cell linesusing large tumorspheres." (PMID 40621031, 2025). "The cytotoxic behavior of complexes 2a–2e was evaluated against four human cell lines: lung adenocarcinoma (A549), melanoma BRAF WT (MeWo), bladder cancer (T24), and a non-malignant skin cell line (HaCaT)." (PMID 40244013, 2025). "Combined BRAF/MEK inhibition with encorafenib (E) plus binimetinib (B) has demonstrated efficacy and tolerability in phase III clinical trials, and is the standard of care for advanced/metastatic BRAFV600-mutant melanoma." (PMID 40078188, 2025). "Also, ctDNA potential as a predictive biomarker of response has been evaluated with other treatment strategies beyond BRAF/MEKi and ICI in melanoma patients." (PMID 39859576, 2025). "In addition to immunotherapy, BRAF and MEK inhibitors (dabrafenib + trametinib) are approved as adjuvant treatment for patients with stage III BRAF-mutant melanoma, based on the COMBI-AD trial." (PMID 40868149, 2025). "BRAF and MEK inhibitors are used in combination to treat non-small-cell lung cancer and melanoma, which harbor BRAF mutations." (PMID 40566099, 2025). "However, it has been shown to discriminate quite accurately poor-prognosis melanoma patients treated with ICI and BRAF/MEKi in clinical trials." (PMID 39859576, 2025). "Our findings demonstrate that targeting mitochondria with DSF shows significant suppression efficacy in BRAFi-resistant melanoma cells, suggesting the combination of DSF with BRAF inhibitors may be a promising strategy to overcome BRAFi resistance." (PMID 40592836, 2025). "This further supports the approach of re-challenge with BRAF and MEK inhibitors in melanoma." (PMID 40066437, 2025). "In the absence of melanoma specific markers, there was substantial risk of misinterpretation as a histiocytic neoplasm as BCL-1, CD68, S100, and, rarely, BRAF expression is potentially supportive of RDD, while BRAF and CD68 are frequently seen in EC." (PMID 40658291, 2025). "Notably, inhibitors like PET-16 demonstrate efficacy in reducing mutant BRAF levels and act synergistically with BRAF inhibitors like PLX4032, potentially overcoming resistance encountered in melanoma patients undergoing BRAF inhibitor treatment." (PMID 40313865, 2025). "Combination treatment with BRAF (vemurafenib, dabrafenib or encorafenib) and downstream MEK (trametinib or binimetinib) inhibitors is recommended for patients with advanced BRAF-mutant melanoma." (PMID 39918770, 2025). "Agents targeting pathways like BRAF and MEK have revolutionized melanoma treatment." (PMID 40963596, 2025).
melanoma (continued). "Future studies should validate these observations in genetically distinct melanoma lines (e.g., BRAF wild-type) and patient-derived xenografts, as well as in non-melanoma models, making it a suitable platform to investigate vesicle remodeling." (PMID 40943445, 2025). "Addition of anti‐PD‐1 to BRAF inhibitor‐based TT appears to be a safe and effective treatment option, conferring a survival benefit and delaying the onset brain metastases in patients with BRAFV600‐mutant advanced melanoma." (PMID 39968494, 2025). "There are clinical differences between BRAF-mutant and BRAF wild-type (BRAFWT) melanomas." (PMID 41010758, 2025). "Activation of ARF6 failed to alter BRAF mRNA levels in A375 melanoma cells, which harbor a homozygous BRAFV600E mutation, demonstrating that ARF6-mediated upregulation of BRAFV600E occurred without altering BRAF oncogene expression." (PMID 40909781, 2025). "BRAF inhibitors such as vemurafenib, by modulating lipid metabolism and enhancing dependence on GPX4, offer novel insights into addressing drug resistance in targeted melanoma therapy." (PMID 39430757, 2024). "Combined therapy against BRAF and MEK is particularly effective in melanoma patients who have not previously been treated with BRAF inhibitors." (PMID 39175042, 2024). "Drug-sensitivity experiments using the FDA-approved BRAF and MEK inhibitors, dabrafenib and trametinib, demonstrated the feasibility of employing melanoma brain metastases patient-derived organoids as models for targeted-therapy in vitro testing and for the discovery of novel therapeutic targets." (PMID 39204387, 2024). "In contrast to pancreatic cancer, melanoma RIPK4 appears not to be a component of the BRAF/MEK/ERK cascade signalling pathway." (PMID 39766280, 2024). "Metastatic melanoma patients are currently treated with iPD-1 monotherapy or with BRAF and MEK inhibitors in the presence of activating BRAF mutations when combined iPD1 and iCTLA4 therapy is not possible." (PMID 39410017, 2024). "Most patients with melanoma LMD do not respond to MAPK-targeting therapies such as the BRAF/MEK inhibitor combination." (PMID 38866016, 2024). "BRAF V600E and V600K mutations are commonly associated with driving melanomagenesis; however, we currently do not have a good understanding of PRAME expression in BRAF V600E versus V600K melanoma." (PMID 39451258, 2024). "CuET and, in particular, the combination caused perinuclear Cu+ accumulation (note: CopperGREENTM reacts only with copper (I) not with copper (II)) in BRAF WT melanoma cells after 6 hours of treatment." (PMID 38263136, 2024). "The major limitation of BRAF/MEK-based targeted therapy is the therapeutic resistance, which can be driven by aberrant pathway activation, metabolic reprogramming, and alterations in melanoma cells’ genetic and epigenetic landscape." (PMID 39582535, 2024). "To date, the efficacy of BRAF/MEK inhibitors in patients with stage II melanoma has not been reported." (PMID 38212945, 2024). "In the context of inhibiting MAPK signaling in melanoma, the development of RAF inhibitors has seen many advancements, with initial, first-generation inhibitors showing effectiveness against active RAF monomers such as BRAF V600E." (PMID 39199684, 2024). "Although NRAS-mutant melanomas represent the most aggressive and second most common melanoma subtype behind BRAF mutant melanomas, there remain no available NRAS-targeted therapies." (PMID 39379700, 2024). "LCH has been reported to occur in two cases secondary to malignant melanoma treatment, although BRAF sequencing was not performed." (PMID 38804700, 2024). "Overall, pending longer survival follow-up, we do not endorse the addition of BRAF-targeted therapy to neoadjuvant ICI in melanoma." (PMID 38907159, 2024). "While limited by the study’s retrospective nature and small sample size, a non-significant trend towards improved OS with dual ICI in BRAF V600 wild-type advanced melanoma was observed." (PMID 39582535, 2024).
melanoma (continued). "BVD-523 is a small-molecule inhibitor of ERK kinase that has completed phase I testing and has demonstrated activity in patients with BRAF/MEK-inhibitor refractory, BRAF-mutant melanoma as well as in a patient with NRAS-mutant melanoma with a reasonable safety profile." (PMID 38683104, 2024). "Following a bilateral mastectomy, the patient was found to have BRAF-negative mucosal melanoma of her hard palate with a soft palate skip lesion." (PMID 38778387, 2024). "Similarly, BRAF, NRAS, and KIT, in the case of melanoma, have led to the development of targeted therapies, which are particularly effective against tumors harboring BRAF mutations." (PMID 39590338, 2024). "Although the results are not as pronounced as those with BRAF and MEK inhibitors, these treatments have shown efficacy in melanomas with KIT mutations." (PMID 39859956, 2024). "Given the good results obtained with BRAF inhibitors for the treatment of BRAF(V600E/K) melanoma, this result was disappointing, and no approval was granted." (PMID 38263136, 2024). "The results were presented as the percentage of the area showing a positive signal.vRT-qPCR analysis of FFPE skin biopsies was performed on the same specimens to determine the fold gene expression score of observed mRNAs between dysplastic nevi, melanoma in situ, and BRAF− and BRAF+ melanoma." (PMID 39273022, 2024). "By comparing the response rates to a reference rate of 15%, the authors concluded that BRAF V600 appeared to be a targetable oncogene in some, but not all, non-melanoma cancers." (PMID 38254740, 2024). "Precisely, this signaling pathway is highly involved in the development of BRAF-mutated melanoma, KRAS/BRAF-mutated colorectal cancer, and metastatic non-small-cell lung cancers." (PMID 38254833, 2024). "To determine the effect of BRAF inhibition on the metabolism of human melanoma cells, we performed in vitro 1H MRS at 9.4T on four melanoma cell lines treated with dabrafenib, a wild-type (WM3918), a resistance mutant-type (WM983BR), and two sensitive mutant-types (WM983B and DB-1)." (PMID 38254853, 2024). "The transition of the melanoma MART-1neg/NGFRhigh subpopulation to the MART-1neg/NGFRneg subpopulation, or the transition of from NRASWT/BRAFV600E to NRASG13R/BRAFV600E following treatment with BRAF inhibitors, has also been reported." (PMID 38275910, 2024). "While Bliss excess showed drug additivity across the entire dose–response landscape in BRAF V600E/K lines, NRAS mutant melanoma lines presented a narrow concentration range in which the combination of panRAF and MEK inhibitors was highly synergized in inhibiting cancer growth." (PMID 39199684, 2024). "Some clinical trials reported that melanoma patients, carried BRAFV600R, achieved favorable outcomes after receiving BRAF/MEK inhibitors, indicating the potential better therapeutic responses of PTC patients carried the novel variant of BRAF after treated with BRAF/MEK inhibitors." (PMID 38241570, 2024). "Since these melanomas can often activate the MAPK pathway through uncommon means, such as CRAF, pan-RAF inhibitors, like sorafenib and AZ628, have been explored on non-V600 BRAF-mutant melanoma samples." (PMID 38732242, 2024). "In this single-center retrospective cohort study, we further analyzed the antitumor activity and safety of triple-targeted therapy (TTT): REGO + BRAF/MEKi, specifically in the AJCC stage IV-M1dBRAF- and NRAS-mutant melanoma patients, refractory to standard-of-care." (PMID 39682270, 2024). "Early attempts at using BRAF inhibitors such as vemurafenib, which has been successful in treating BRAF-mutant melanoma, showed limited efficacy in CRC, mostly due to rapid reactivation of EGFR signaling, a compensatory mechanism that allows cancer cells to bypass BRAF inhibition." (PMID 39684219, 2024).
melanoma (continued). "Moreover, compared to BRAF-mutant tumors, NRAS-mutant melanomas tend to be thicker, with increased mitotic rates, usually occurring in older patients (>55 years) with a history of chronic UV exposure." (PMID 38396984, 2024). "Most patients were men (61.9%), had an ECOG performance status of 0 (81.0%), had BRAF wild‐type disease (78.6%), had a normal level of lactate dehydrogenase (97.6%), and had received no prior systemic therapy for advanced melanoma (59.5%)." (PMID 38529706, 2024). "Furthermore, additional studies will be required to determine the optimal protocols of neoadjuvant/adjuvant therapy for BRAF-WT and BRAF-mutant stage II-III melanomas." (PMID 39727691, 2024). "This review provides a comprehensive overview of the current state of BRAF-targeted therapies in melanoma, highlighting the efficacy and limitations of FDA-approved combinations of BRAF and MEK inhibitors such as vemurafenib, dabrafenib, trametinib, and cobimetinib." (PMID 39582535, 2024). "Fifteen cases had BRAF wild-type melanoma (68%), six had BRAFV600E-mutated melanoma (27%) and one case was not evaluated (5%)." (PMID 39337055, 2024). "The genomic landscape of high-CSD melanomas differs from non- or low-CSD melanomas and they typically do not harbor the signature BRAF V600E mutations." (PMID 38247727, 2024). "The first one is that miR-579-3p is specifically deregulated in the subset of BRAF-mutant melanomas but not in BRAF wt tumors and that its levels mirror those of MITF." (PMID 38472212, 2024). "Our inclusion criteria were broad, including studies with both BRAF-mutant and BRAF wild-type melanomas without distinguishing the byline of therapy." (PMID 39684531, 2024). "While BRAF and MEK inhibition is a common tactic for treating melanoma, ERK-specific targeting has been rare despite its placement downstream of both BRAF and MEK, which has a more direct effect on the genetic and proliferative effects of the MAPK signaling pathway." (PMID 38732242, 2024). "We show here that the 50% decrease in BRAF-RAF1 heterodimer formation does not phenocopy BRAF depletion in terms of melanoma TEM." (PMID 39457016, 2024). "Our results showed that Panx1 global deletion did not reduce the strong BRAF/Pten‐driven melanoma progression but increased the tumor infiltration of effector immune T‐cell populations." (PMID 38327091, 2024). "Disulfiram and its metabolite represent an attractive pharmaceutical approach to induce ER stress in melanoma cells that potentiates the antitumor effect of MEK inhibition and may be an interesting candidate for combination therapy of BRAF WT melanoma." (PMID 38263136, 2024). "Inhibition of the MAPK signalling pathway through agents such as dabrafenib, vemurafenib, binimetinib, encorafernib, trametinib, selumetinib, and cobimetinib, which bind to signal cascade kinases BRAF and MEK, has become a crucial treatment strategy for patients with BRAF-mutant melanoma." (PMID 38334660, 2024). "Over the last decade, there has been a revolutionary transformation in the clinical treatment of individuals with advanced melanoma, brought about by the adoption of immunotherapies targeting PD1 and/or CTLA-4, along with targeted therapies inhibiting BRAF/MEK." (PMID 38539531, 2024). "Both nivolumab and pembrolizumab can be considered as options in high risk for relapse resected melanoma—IIIA–IIIC pembrolizumab, IIIB–IV nivolumab—regardless of BRAF status (level of evidence 1, grade of recommendation A)." (PMID 38748192, 2024). "Here, we report on the discovery of a melanoma-associated lncRNA that we named ‘T-RECS’, and that is significantly upregulated in NRAS-/BRAF-mutated cell lines and patient tumors compared to normal/non-malignant cells or tissues." (PMID 38383439, 2024).